SNAI1 (snail family transcriptional repressor 1)
Diseases named in the same sentence as SNAI1 in open-access papers (continued):
Sharing a sentence is not in itself a finding about the gene and the disease.
rheumatoid arthritis (2 papers, 2017 to 2025). A chronic, systemic autoimmune disorder characterized by inflammation in the synovial membranes and articular surfaces. "IL‐6 activates YAP through JAK, promoting YAP–Snail family transcriptional repressor 1 (SNAIL) interactions that drive the pathogenic transformation of rheumatoid arthritis synovial fibroblasts, ultimately leading to joint destruction." (PMID 40066231, 2025).
serous ovarian cancer (2 papers, 2021 to 2024). "Increased expression of all the selected genes except NECTIN4 and SNAI1 showed significant correlation with poor clinical outcomes in patients with serous ovarian cancer, but not with the endometrioid subtype." (PMID 34868914, 2021).
Ureteral obstruction (2 papers, 2018 to 2021). Obstruction of the flow of urine through the ureter. "Administration of ICG-001 abolished the expression of Fn1 and Inhba which was induced by the ureteral obstruction and reduced the expression of the Wnt target gene, Snai1." (PMID 30075015, 2018).
viral infection (2 papers, 2024). "SNAI1 is a direct target of IRF3, and viral infection as well as intracellular Poly I:C treatment have been shown to induce SNAI1 and SNAI2 expression." (PMID 39159817, 2024).
acute monocytic leukemia (1 paper, 2023). Acute monoblastic leukemia (AML-M5), is one of the most common subtypes of acute myeloid leukemia (AML) that is either comprised of more than 80% of monoblasts (AML-M5a) or 30-80% monoblasts with (pro)monocytic differentiation (AML-M5b). "In contrast to the healthy immune system, SNAI1 has been shown to contribute to pathogenesis in acute monocytic leukemia (AML)." (PMID 36923642, 2023).
adenosarcoma (1 paper, 2017). A low grade malignant neoplasm characterized by the presence of a benign epithelial component (tubular and cleft-like glands) and a low grade sarcomatous component that contains varying amounts of fibrous and smooth muscle tissues. "TGFβ induces EMT in many types of cells in vitro, including human ovarian epithelial and adenosarcoma cells, by enhancing Snai1 (Snail) expression leading to inhibition of Cdh1 (E-cadherin)." (PMID 29100356, 2017).
allergic asthma (1 paper, 2013). A asthma with a basis in a pathological type I hypersensitivity reaction. "We note that airways infection with respiratory syncytial virus (RSV), the most common viral respiratory pathogen in small children which is widely considered as a risk factor for the development of allergic asthma later in life is characterized by an increased expression of SNAI1, MMP-2, and TGFβ1." (PMID 24228254, 2013).
ameloblastoma (1 paper, 2020). The most common odontogenic tumor, arising from the epithelial component of the embryonic tooth and usually affecting the molar-ramus region of the mandible or maxilla. "Interestingly, we found that TGF‐β signaling‐related genes including transforming growth factor beta 3 (TGFB3), snail family transcriptional repressor 1 (SNAI1), and inhibitor of DNA binding 3 (ID3) were significantly activated in ameloblastoma tumors." (PMID 32096304, 2020).
chronic obstructive pulmonary disease (1 paper, 2020). A chronic and progressive lung disorder characterized by the loss of elasticity of the bronchial tree and the air sacs, destruction of the air sacs wall, thickening of the bronchial wall, and mucous accumulation in the bronchial tree. "For example, among the 4 chronic obstructive pulmonary disease (COPD)–associated proteins shown in the network, TGFB1 is the direct target of HCoV-229E, and all 4 proteins (TGFB1, DEFB1, SNAI1, and ADAM33) interact with at least 1 SARS-CoV-2 target protein." (PMID 33156843, 2020).
colorectal adenoma (1 paper, 2012). An adenoma that arises from the colon or rectum. "As in our current study on colorectal adenoma tissue, they observed in diffuse gastric cancer that increased SNAI1 mRNA expression was associated with down-regulation of CDH1 mRNA." (PMID 23029563, 2012). "In conclusion, our hypothesis generating study revealed SNAI1 expression as well as combined SNAI1/TWIST expression to be associated with decreased expression of CDH1 in colorectal adenomas." (PMID 23029563, 2012). "Therefore, further investigation might be beneficial to check the use of TWIST1 and SNAI1 as markers for high-risk colorectal adenomas." (PMID 23029563, 2012). "Analysing an unselected cohort of colorectal adenomas, we were therefore surprised by the relatively high frequency of SNAI1 and TWIST1 mRNA expression, which was quite similar to the published expression rates in CRC tissue." (PMID 23029563, 2012). "This correlation further indicated an influence of SNAI1 on the expression of E-Cadherin in colorectal adenomas." (PMID 23029563, 2012). "On the transcriptional level, we observed a significant correlation between SNAI1/Snail1 expression and CDH1/E-cadherin loss in colorectal adenomas." (PMID 23029563, 2012). "Strikingly, mRNA expression of SNAI1 was significantly correlated with decreased levels of CDH1 mRNA in colorectal adenomas, suggesting an “active” CDH1 suppression by the transcription factor SNAI1." (PMID 23029563, 2012). "When comparing the amount of CDH1 mRNA in colorectal adenomas with or without SNAI1 expression, we found a significant difference." (PMID 23029563, 2012). "Here we tested whether the important regulators of E-cadherin expression SNAI1 and TWIST1 are already detectable in human colorectal adenomas." (PMID 23029563, 2012). "We found the same significant correlation between Snail1 positive colorectal adenomas and a high amount of SNAI1 mRNA, as well as between Snail1 negative colorectal adenomas and low amounts of SNAI1 mRNA (p = 0.001, Mann-Whitney-U test)." (PMID 23029563, 2012). "We could detect SNAI1 mRNA expression in 32 (78%) and TWIST1 mRNA expression in 17 (42%) of 41 colorectal adenomas." (PMID 23029563, 2012). "In the 32 colorectal adenomas, which were positive for SNAI1 mRNA, the amount of CDH1 mRNA was significantly lower (p = 0.004, Mann-Whitney-U test), compared to the amount in colorectal adenomas without SNAI1 mRNA expression." (PMID 23029563, 2012). "SNAI1 mRNA was expressed in 78% (n = 32/41), TWIST1 mRNA in 41% (n = 17/41) and CDH2 mRNA in 41% (n = 17/41) of the colorectal adenoma tissue, while normal colon mucosa was negative for these transcription factors." (PMID 23029563, 2012).
diabetic neuropathy (1 paper, 2023). A chronic, pathological complication associated with diabetes mellitus, where nerve damages are incurred due to diabetic microvascular injury involving small blood vessels that supply these nerves, resulting in peripheral and/or autonomic nerve dysfunction. "The serine protease inhibitor α2-antiplasmin similarly bypasses TGF-β and induces Smad2/3 activation via AGE-induced responses.The SET domain-containing protein 8 (SETD8) regulates EndMT in diabetic neuropathy by directly regulating SNAI1; upregulation of SETD8 suppressed SNAI1, and prevented EndMT." (PMID 36777351, 2023).
endometrioid endometrial carcinoma (1 paper, 2020). "When compared with the normal endometrium, SNAI1 was upregulated as early as in the noninvasive (stage 1A) and myoinvasive (stage 1B) tumors, followed by the expression of TWIST1, ZEB1, and SNAI2 in the myoinvasive (stage 1C) tumors of endometrioid endometrial carcinoma." (PMID 32370157, 2020).
hypopituitarism (1 paper, 2023). A condition of diminution or cessation of secretion of one or more hormones from the anterior pituitary gland. "Moreover, vimentin and SNAI1 overexpression showed an association with tumors presenting, respectively, headache and hypopituitarism before surgery (p=0.050 and p=0.048)." (PMID 37033229, 2023).
invasive carcinoma (1 paper, 2017). A carcinoma that is not confined to the epithelium, and has spread to the surrounding stroma. "Activation of the EMT-inducing transcription factor, SNAI1, can be clearly demonstrated in invasive carcinomas." (PMID 29163781, 2017).
iron deficiency (1 paper, 2013). "Most importantly, it not only reduced tumor growth and lung metastasis, but also reversed iron deficiency-mediated upregulation of Snai1 and Notch and downregulation of E-cadherin." (PMID 23800380, 2013). "Consistent with qPCR results, protein levels of E-cadherin were dramatically decreased but levels of Snai1 were greatly augmented by iron deficiency." (PMID 23800380, 2013). "Not only did iron therapy reverse lung metastasis, but also reversed iron deficiency-mediated tumor growth, downregulated Snai1, upregulated E-cadherin, and decreased Notch2 expression." (PMID 23800380, 2013).
lentivirus infection (1 paper, 2024). Virus diseases caused by the Lentivirus genus. "To further demonstrate the importance of SNAI1 in the reprogramming of MEFs, we utilized lentivirus infection to overexpress SNAI1 in MEFs and subsequently treated these cells with SMC for 12 days." (PMID 37996395, 2024).
lymphoma (1 paper, 2023). A malignant (clonal) proliferation of B- lymphocytes or T- lymphocytes which involves the lymph nodes, bone marrow and/or extranodal sites. "To date, no studies have looked specifically at SNAI1 in lymphoid malignancies, however the Combi-tTA-Snai1 transgenic mice do develop lymphomas in 50% of cases suggesting SNAI1 should be considered in the context of human lymphomas as well." (PMID 37600794, 2023).
malignant peripheral nerve sheath tumor (1 paper, 2019). Malignant peripheral nerve sheath tumor (MPNST) is a rare and often aggressive soft tissue sarcoma occurring in a wide range of anatomical sites. "EMT-associated transcription factors such as SNAIL (SNAI1), SLUG (SNAI2), Twist Family BHLH Transcription Factor (TWIST)-1, Zinc Finger E-Box Binding Homeobox (ZEB) have been shown to be upregulated in malignant peripheral nerve sheath tumor (MPNST) deficient for neurofibromin." (PMID 30967630, 2019).
mandibular deficiency (1 paper, 2023). "The neural crest-specific deletion of Snai1 on a Snai2−/− background results in multiple craniofacial defects including mandibular deficiency similar to the Pierre Robin sequence, indicating that SNAIL genes can modulate jaw growth." (PMID 36768894, 2023).
myeloid leukemia (1 paper, 2021). A clonal proliferation of myeloid cells and their precursors in the bone marrow, peripheral blood, and spleen. "Further studies are clearly required to determine the degree of synergy and crosstalk between ZEB1/2 and SNAI1 in AML as well as their common and unique underlying molecular roles in driving myeloid leukemia." (PMID 34550965, 2021).
Nm (1 paper, 2019). "In agreement with the mentioned observations of tight junction disruption, Nm infection of iPSC-BECs upregulated host SNAI1 (Snail-1), a transcriptional repressor of tight junction components operating in the infection mechanisms of Group B Streptococcus." (PMID 31191497, 2019).
ovarian clear cell cancer (1 paper, 2023). An invasive malignant neoplasm that arises from the ovary and is characterized by a predominance of clear and hobnail malignant epithelial cells. "Left–right determination factor (LEFTY), a member of the TGF-β superfamily, was reported to be involved in the TGF-β/Smad/SNAI1 signalling for EMT induction in ovarian clear cell carcinoma cells." (PMID 36766756, 2023).
pterygium (1 paper, 2021). A wedge-shaped fibrovascular lesion arising from the bulbar conjunctiva and extending to the cornea. "An increase in EMT in corneal epithelium in pterygium is also suggested, regulated by KLF7, BMP2, BMP6, and SNAI1." (PMID 34769520, 2021). "Our further analysis of pathways controlled by upstream regulator TP63 suggested increased EMT in pterygium, regulated by BMP2, BMP6, SNAI1 and KLF7." (PMID 34769520, 2021). "A previous study detected immunoreactive SNAI1 protein throughout the epithelium of pterygium, but not healthy corneal epithelium." (PMID 34769520, 2021).
renal cell adenocarcinoma (1 paper, 2021). A carcinoma arising from the renal parenchyma. "In human renal cell adenocarcinoma cell lines, the expression of the snail family transcriptional repressor 1 (SNAI1) is promoted by ACSS2." (PMID 34572472, 2021).
steatosis (1 paper, 2022). Increased lipid within the cytoplasm of cells. "In this study, we identified that ISL1 had interacted with H3K27me3 demethylase KDM6B to promote the expression of SNAI1, by which lipogenesis and steatosis were attenuated while lipolysis was promoted in the mice models of NAFLD." (PMID 35100965, 2022).
tumor (910 papers, 2005 to 2026). "Similar to the influence of USP47 depletion on GC tumor cellular phenotype, Snai1 deficiency profoundly inhibited cell proliferation, colony-forming capability, cell migration, and invasion." (PMID 39998882, 2025). "It is well established that Snai1 transcription factor overexpression is associated with increased tumor migration and invasion via induction of EMT." (PMID 35683135, 2022). "Snail (encoded by SNAI1) is a key transcriptional repressor of E-cadherin expression that can regulate tumor metastasis." (PMID 35927236, 2022). "First, more clinical samples should be collected to examine the expression levels of miR-30e-5p and SNAI1 as well as their association with various clinical parameters, such as tumor grade and stage." (PMID 35300562, 2022). "TGF-β has been classically associated in TNBC with metastasis and tumor invasion through facilitation of epithelial-to-mesenchymal transition (EMT)—a process which can be typically characterized via induction of SNAI1/TWIST1/TWIST2/ZEB1 gene expression." (PMID 35326728, 2022). "EMT‐associated TF Snai1 and tumor invasive marker MMP‐9 showed elevated expression in the FSS‐HepG2 cells." (PMID 34260811, 2021). "Accordingly, in human HCC, we observed that a low SNAI1 promoter methylation is a risk factor for tumor recurrence and metastasis." (PMID 34571856, 2021). "In other cancer types, the depletion of SNAI1 causes changes in tumor secretome, specifically by increasing GM-CSF production, leading to an altered TAM polarization that is inclined toward M1-like macrophages." (PMID 34207850, 2021). "EMT in tumor cells is closely associated with the expression of E-cadherin (E-ca), the transcription factor Snail (SNAI1), and N-cadherin (N-ca)." (PMID 32432570, 2020). "Expression of SNAI1 is positively associated with tumor grade, recurrence, and metastasis as well as with poor prognosis in individuals with various tumor types." (PMID 32429232, 2020). "miR-153 is an ancient and conserved miRNA which suppresses the tumor development by downregulating tumor-associated genes, such as SNAI1, KLF5, and MCL-1." (PMID 29959560, 2018). "We found that these events occurred in tumor-bearing iron deficient mice, as mRNA levels of Snai1, 2 and Zeb1, 2 were upregulated at least one-fold in the primary tumors of mice fed an iron deficient diet." (PMID 23800380, 2013). "High level SNAI1 expression (>10% tumor cells) was rare, but significantly associated with poor outcome." (PMID 20181105, 2010). "Closer examination of the SNAI1(+) group of cases revealed 2 patients with distinct SNAI1-expressing tumor areas of 80% and 30% associated with p63 loss." (PMID 20181105, 2010). "Snail family transcriptional inhibitory protein 1 (SNAI1) is a zinc-finger transcription factor that downregulates E-calmodulin expression through specific recognition of its promoter and is closely associated with tumour development." (PMID 40028162, 2025). "Furthermore, endothelial-specific knock-out of Snai1 delays the appearance of experimental breast tumors and influences associated stroma formation, immune cell infiltration, and tumor phenotype." (PMID 39095583, 2024). "X-ray exposure of hypoxic A549 cells also upregulated the expression of an EMT transcription factor gene, specifically snail family transcriptional repressor 1 (SNAI1), which was recently reported to be associated with tumor progression and aggressiveness in NSCLC." (PMID 38674080, 2024). "We also found that SNAI1 was associated with tumor invasion and poor SRL response." (PMID 35203668, 2022). "Notably, log-rank test showed that increased expression of IRP2 in tumor were associated with poor OS, while increased expression of SNAI1 was associated with poor PFS." (PMID 34733841, 2021).